PSMD8 (proteasome 26S subunit, non-ATPase 8)
Description:
Component of the 26S proteasome, a multiprotein complex involved in the ATP-dependent degradation of ubiquitinated proteins. This complex plays a key role in the maintenance of protein homeostasis by removing misfolded or damaged proteins, which could impair cellular functions, and by removing proteins whose functions are no longer required. Therefore, the proteasome participates in numerous cellular processes, including cell cycle progression, apoptosis, or DNA damage repair.
Synonyms: S14; Nin1p; p31; HIP6; HYPF; Rpn12; HEL-S-91n
Tractability: Small molecule: an approved drug acts on it; a structure with a bound ligand is known; a high-quality ligand is known. PROTAC: UniProt records ubiquitination sites on it; ubiquitination databases record sites on it; its protein half-life has been measured.
Target class: Enzyme
Gene: Protein-coding gene on chromosome 19 (38,374,563 to 38,383,850, forward strand). Ensembl gene ENSG00000099341.
Subcellular location (Human Protein Atlas): Cytosol; Nuclear speckles
Pathways (Reactome):
Immune System: AMPK-induced ERAD and lysosome mediated degradation of PD-L1(CD274); Activation of NF-kappaB in B cells; Antigen processing: Ubiquitination & Proteasome degradation; CLEC7A (Dectin-1) signaling; Cross-presentation of soluble exogenous antigens (endosomes); Dectin-1 mediated noncanonical NF-kB signaling; Downstream TCR signaling; ER-Phagosome pathway; FCERI mediated NF-kB activation; GSK3B-mediated proteasomal degradation of PD-L1(CD274); Interleukin-1 signaling; NIK-->noncanonical NF-kB signaling; SPOP-mediated proteasomal degradation of PD-L1(CD274); TNFR2 non-canonical NF-kB pathway
Cell Cycle: APC/C:Cdc20 mediated degradation of Securin; APC/C:Cdh1 mediated degradation of Cdc20 and other APC/C:Cdh1 targeted proteins in late mitosis/early G1; Autodegradation of Cdh1 by Cdh1:APC/C; Autodegradation of the E3 ubiquitin ligase COP1; Cdc20:Phospho-APC/C mediated degradation of Cyclin A; FBXL7 down-regulates AURKA during mitotic entry and in early mitosis; G2/M Checkpoints; SCF(Skp2)-mediated degradation of p27/p21; SCF-beta-TrCP mediated degradation of Emi1; Separation of Sister Chromatids; The role of GTSE1 in G2/M progression after G2 checkpoint; Ubiquitin-Mediated Degradation of Phosphorylated Cdc25A; Ubiquitin-dependent degradation of Cyclin D
Signal Transduction: Asymmetric localization of PCP proteins; Degradation of AXIN; Degradation of DVL; Degradation of GLI1 by the proteasome; Degradation of GLI2 by the proteasome; Degradation of beta-catenin by the destruction complex; GLI3 is processed to GLI3R by the proteasome; Hedgehog 'on' state; Hedgehog ligand biogenesis; MAPK6/MAPK4 signaling; Negative regulation of NOTCH4 signaling; Regulation of PTEN stability and activity; Regulation of RAS by GAPs
and 27 more pathways
Gene Ontology:
Molecular function: protein binding
Biological process: cellular response to type I interferon; proteasomal protein catabolic process; proteasome-mediated ubiquitin-dependent protein catabolic process; regulation of proteasomal protein catabolic process; response to oxidative stress; proteolysis
Cellular component: nucleus; proteasome complex; cytosol; nucleoplasm; proteasome accessory complex; proteasome regulatory particle; proteasome regulatory particle, lid subcomplex; synaptic vesicle; protein-containing complex
Genetic constraint (gnomAD): Loss-of-function variants: 30 observed, 32.54 expected, observed/expected ratio (o/e) 0.92, 90% interval 0.69 to 1.25. The synonymous counts are far from expectation, so gnomAD's model fits this gene poorly and the ratio says little. Missense variants: 461 observed, 393.06 expected, observed/expected ratio (o/e) 1.17, 90% interval 1.09 to 1.27. Synonymous variants: 208 observed, 163.02 expected, observed/expected ratio (o/e) 1.28, 90% interval 1.14 to 1.43.
Homologues: Orthologues: chimpanzee PSMD8 (100% identical), pig PSMD8 (92% identical), rabbit PSMD8 (92% identical), dog PSMD8 (91% identical), guinea pig PSMD8 (91% identical), rat Psmd8 (91% identical), mouse Psmd8 (90% identical), macaque PSMD8 (78% identical), tropical clawed frog psmd8 (68% identical), zebrafish psmd8 (63% identical), Drosophila melanogaster Rpn12 (37% identical), Drosophila melanogaster Rpn12R (31% identical), and 1 more.
Diseases named in the same sentence as PSMD8 in open-access papers:
PSMD8 is named in the same sentence as 23 diseases in open-access papers, as found by Europe PMC text mining. Sharing a sentence is not in itself a finding about the gene and the disease. The quoted sentences say what the papers report.
breast carcinoma (3 papers, 2017 to 2022). "PSMD8 was found to be overexpressed or mutated in breast cancer and diffuse large B cell lymphoma." (PMID 35846349, 2022). "In this context, Deng and colleagues demonstrated that the expression of six proteasome subunits including PSMA1, PSMB5, PSMD1, PSMD2, PSMD8 and PSMD11 was increased over three-fold in breast cancer tissues when compared to adjacent normal tissues." (PMID 27966459, 2017).
diffuse large B-cell lymphoma (2 papers, 2022 to 2023). "GEPIA website data analysis showed that PSMD8 is highly expressed in ovarian cancer, pancreatic cancer, gastric cancer, thymic cancer, glioblastoma multiforme, and diffuse large B-cell lymphoma, while it is lowly expressed in acute myeloid leukemia." (PMID 37349676, 2023).
cardiac hypertrophy (1 paper, 2022). "Moreover, transcriptome unbiased analysis of post-MI cardiomyocytes with GRK5 overexpression showed altered levels of several genes previously indicated to be involved in cardiac hypertrophy, remodeling or HF such as Kcne1, Efna5, Psmd8 and several regulators of the extracellular matrix." (PMID 33560342, 2022).
diabetes (1 paper, 2020). "In the group enriched with diabetic patients (6 out of 9 patients), seven proteasome genes (PSME4, PSMA7, PSMB4, PSMB6, PSMC4, PSMD7 and PSMD8) and three genes previously associated with common diabetes (SNX17, PARK7/DJ-1 and ATP5B) were highly expressed." (PMID 32302349, 2020).
glioma (1 paper, 2023). A benign or malignant brain and spinal cord tumor that arises from glial cells (astrocytes, oligodendrocytes, ependymal cells). "TCGA database showed that among malignant tumors, PSMD8 was more frequently expressed in ovarian cancer, testicular cancer, glioma, and melanoma." (PMID 37349676, 2023).
mesothelioma (1 paper, 2022). A usually malignant and aggressive neoplasm of the mesothelium which is often associated with exposure to asbestos. "A Kaplan-Meier survival analysis revealed that high expressions of AUNIP, FANCI, LASP1, PSMD8, and XPO5 were clearly associated with poor OS and RFS, suggesting that the five candidate genes play important roles in the tumorigenesis and progression of mesothelioma." (PMID 35846349, 2022). "AUNIP, FANCI, LASP1, PSMD8, and XPO5 are putative antigens for the development of anti-mesothelioma mRNA vaccine and patients with the IS1 subtype may be considered for vaccination." (PMID 35846349, 2022).
ovarian carcinoma (1 paper, 2023). A malignant neoplasm originating from the surface ovarian epithelium. "The expression levels of PSMD8/14 mRNA in ovarian cancer tissues were significantly higher than those in normal ovarian tissues, and the expression levels of PSMD2/3/4/5/8/11/12/14 mRNA were associated with prognosis." (PMID 37349676, 2023). "In vitro experiments as well as analysis of the relationship of PSMD8 expression in ovarian cancer with the clinicopathological parameters and survival outcomes showed that PSMD8 overexpression can enhance malignant biological behavior of ovarian cancer." (PMID 37349676, 2023). "Overexpression of PSMD8 significantly enhanced the proliferation, migration, and invasion abilities in ovarian cancer cells." (PMID 37349676, 2023). "On analyzing the relationship of PSMD family and ovarian cancer, the expression levels of PSMD8 and PSMD14 mRNA in ovarian cancer were found to be significantly higher than those in normal ovarian tissue." (PMID 37349676, 2023). "The TISIDB database was used to analyze the correlation between PSMD8 and immunity, and the role of PSMD8 in ovarian cancer tissue was verified by immunohistochemical experiments." (PMID 37349676, 2023). "In conclusion, PSMD8 has a higher abnormal expression in ovarian cancer." (PMID 37349676, 2023). "The mRNA expression levels of PSMD8 and PSMD14 in ovarian cancer tissues were significantly higher than those in normal ovarian tissues." (PMID 37349676, 2023).
ovarian epithelial malignant tumor (1 paper, 2023). "Furthermore, immunohistochemical experiments demonstrated that PSMD8 was mainly expressed in the cytoplasm, and was highly expressed in ovarian epithelial malignant tumor tissues, and the expression level showed a correlation with FIGO stage." (PMID 37349676, 2023).
ovarian serous carcinoma (1 paper, 2023). "Among them, up-regulation of PSMD4, PSMD8, and PSMD14 mRNA expression was significantly associated with poor OS in patients with ovarian serous carcinomas." (PMID 37349676, 2023). "On comprehensive comparison, up-regulation of PSMD8 mRNA expression was significantly associated with poor OS and PFS in patients with ovarian serous carcinomas." (PMID 37349676, 2023).
Stroke (1 paper, 2020). Sudden impairment of blood flow to a part of the brain due to occlusion or rupture of an artery to the brain. "Still, stroke induced differential expression of several genes related to the ubiquitin-proteasome pathway, although, Myog, Cblb, Nf32l1, Psmd8, and Trp63 were significantly upregulated ≥2-fold." (PMID 32629989, 2020).
urothelial bladder carcinoma (1 paper, 2023). "In urothelial bladder carcinoma, PSMD2, PSMD3, PSMD4, PSMD8, and PSMD11 genes are overexpressed." (PMID 36934426, 2023).
cancer (5 papers, 2014 to 2024). A tumor composed of atypical neoplastic, often pleomorphic cells that invade other tissues. "The mRNA expression of PSMD8 in normal tissues and cancer tissues was analyzed using the human protein atlas website, and the results showed greater expression of PSMD8 in normal skeletal muscle, cardiac muscle, and tongue muscle." (PMID 37349676, 2023). "Also, in the Basal subtype, PSMD8 is involved in protein degradation via the ubiquitin–proteasome system, which is crucial for maintaining protein homeostasis in cancer cells." (PMID 39596229, 2024).
tumor (4 papers, 2012 to 2024). "The high recurrence of genes like C1QBP and RPS3A in Luminal A, USP31 and RRM1 in Luminal B, and PSMD8 and YME1L1 in Basal subtypes highlights the subtype-specific regulatory networks that underlie tumor progression." (PMID 39596229, 2024). "In this study, we identified five tumor antigens (AUNIP, FANCI, LASP1, PSMD8, and XPO5) that were considered promising candidates as mRNA-based vaccines." (PMID 35846349, 2022). "A total of five potential tumor antigens correlated with prognosis and infiltration of antigen-presenting cells, including AUNIP, FANCI, LASP1, PSMD8, and XPO5 were identified." (PMID 35846349, 2022). "AUNIP, FANCI, LASP1, PSMD8, and XPO5 are putative tumor antigens for mRNA vaccine development." (PMID 35846349, 2022). "Therefore, immunotherapy using mRNA vaccines targeting previously recognized tumor antigens (AUNIP, FANCI, LASP1, PSMD8, and XPO5) could induce immune cell infiltration to reinvigorate the ISI patient’s immune system." (PMID 35846349, 2022).
infection (1 paper, 2022). The state of being infected such as from the introduction of a foreign agent such as serum, vaccine, antigenic substance or organism. "In addition, in the coinfection group, the relative expression of PSMD8 was more than 250 times higher than that of the single infection group." (PMID 35309129, 2022).
PSMD8 also shares sentences with these, for which no sentence is quoted: acute myeloid leukemia (1 paper); chronic myeloid leukemia (1); colon cancer (1); gastric cancer (1); glioblastoma multiforme (1); melanoma (1); pancreatic cancer (1); serous ovarian cancer (1); testicular cancer (1).